SIRT1 (sirtuin 1)
Diseases named in the same sentence as SIRT1 in open-access papers (continued):
Sharing a sentence is not in itself a finding about the gene and the disease.
glomerulosclerosis (14 papers, 2020 to 2025). A hardening of the kidney glomerulus caused by scarring of the blood vessels. "Podocyte-specific SIRT1 KO in mice aggravated aging-associated glomerulosclerosis and albuminuria and was associated with an increase in cellular oxidative stress, measured by urinary 8-hydroxy-2′-deoxyguanosine (8-OHdG), and reduced podocyte maturation." (PMID 38069234, 2023). "NMN attenuated the rate of NAD+ synthesis in adriamycin-treated mice with increased urinary albumin excretion, attenuated glomerulosclerosis, reduced Sirt1 expression, and elevated claudin-1 expression in mouse kidneys." (PMID 38347622, 2024). "Resveratrol treatment has been demonstrated to reduce renal oxidative stress and prevent Con A-induced progressive glomerulosclerosis through SIRT1-mediated Klotho expression in old mice." (PMID 38069234, 2023). "In contrast, specific SIRT1 stimulation in the ADR + SRT1720 group attenuated the glomerulosclerosis index, tubular damage, and tubular protein cast formation and reduced kidney damage." (PMID 38114708, 2023). "NMN treatment mitigated glomerulosclerosis and ameliorated the reduced Sirt1 expression and elevated Claudin-1 expression in the kidneys of the mice." (PMID 35962139, 2022). "Partial knockdown of SIRT1 in renal podocytes intensifies glomerulosclerosis in aged mice and is accompanied by an increased urinary 8-OH-dG level." (PMID 32942691, 2020). "Our data indicated that resveratrol pretreatment protected against Con A-induced advanced glomerulosclerosis in aged mice by attenuating renal oxidative stress, at least in part, through SIRT1-mediated klotho expression." (PMID 32942691, 2020). "Not surprisingly, activators of SIRT1, for example, resveratrol, show promising results in arresting high glucose‐induced kidney cell senescence, with recent findings in aged mice reporting that resveratrol protects against glomerulosclerosis through SIRT1‐mediated klotho expression." (PMID 38995865, 2025). "However, another study revealed that podocyte-specific METTL14 deletion upregulated Sirt1 expression, thereby alleviating apoptosis and inflammation, regulating autophagy, and delaying the development of proteinuria and glomerulosclerosis." (PMID 36157472, 2022). "Moreover, the reduced expression of SIRT1 in podocytes plays an important role in age-induced kidney injury, aggravating glomerulosclerosis and albuminuria, as indicated by the increased expression of cellular senescence markers." (PMID 35277012, 2022). "Mice with podocyte-specific Sirt1 knockdown increase their inflammation-related markers and exacerbate NLRP3 inflammatory vesicle activation, leading to increased glomerulosclerosis and proteinuria." (PMID 38347622, 2024). "Therefore, we speculate that Con A-induced severe albuminuria and advanced glomerulosclerosis are highly correlated with increased renal oxidative stress via the repression of SIRT1-mediated klotho expression and that these effects are attenuated by resveratrol pretreatment." (PMID 32942691, 2020). "Furthermore, the Sirt1 activator NMN—an NAD+-dependent deacetylase enhancer—improves podocyte injury and glomerulosclerosis by upregulating Sirt1 and the NAD+ salvage pathway, including Nampt and Nmnat1." (PMID 41487503, 2025). "SRT3025 also activates Sirt1 and has been reported to reverse the increase in collagen production due to TGF-β1 stimulation, reduce glomerulosclerosis and tubulointerstitial fibrosis, and attenuate the decrease in the glomerular filtration rate and proteinuria." (PMID 38347622, 2024). "In a mouse model of age-related renal injury, SIRT1/AMPK and PPARα signaling were downregulated, while resveratrol improved the renal function, proteinuria, and glomerulosclerosis by activating NRF2 signaling and activating SIRT1/AMPK and PPARα signaling in the kidney." (PMID 34942962, 2021).
skin cancer (14 papers, 2010 to 2021). "The wild type and heterozygous for Sirt1 mice are prone to skin cancer development due to reduced DNA repair and cell survival, whereas Sirt1-homodeficiency increases apoptosis signaling and decreases tumorigenesis, but sensitizes skin to solar injury." (PMID 33917352, 2021). "Modulation of SIRT1 activity may constitute a novel approach to photoprotection, and hold a great potential for improving outcomes in patients with skin cancers." (PMID 33917352, 2021). "Importantly, Sirt1 deletion reduced the ability of resveratrol to protect against skin cancer in mice." (PMID 32210296, 2020). "Although the role of SIRT1 in cancer development is still under debate, SIRT1 levels are significantly reduced in human skin tumors, suggesting that SIRT1 may act as a tumor suppressor through its role in DNA repair." (PMID 31779194, 2019). "Accumulating evidence indicates that the role of SIRT1 in skin cancer is complex." (PMID 26437418, 2015). "Recently, a dual role of SIRT1 in a model of UVB-induced skin cancer was reported." (PMID 26437418, 2015). "In addition, Sirt1 is a key modulator of cellular pathways involved in inherited dermatologic diseases and skin cancers, suggesting that Sirt1 activation is a molecular target for dermatological therapy." (PMID 26180586, 2015). "The SIRT1 inhibitor Cambinol and Tenovin-6 have shown promising anti-cancer effects in a range of cancer cell lines and in animal models of Burkitt's lymphoma and skin cancer." (PMID 21698133, 2011). "Experimental studies support the conclusion that SIRT1 may prevent UVR-related premature aging and skin cancer development." (PMID 33917352, 2021). "We suspected that increasing the expression of SIRT1 or decreasing the expression of miR‐27a‐5p may reduce UVA‐related diseases, or even play a role in the treatment of UVA‐induced skin cancer." (PMID 32790210, 2020). "The development of NSAIDs-derived SIRT1 inhibitors may provide a valid alternative in case the chemopreventive activity of nicotinamide would not be proven efficacious for tumours other than skin-cancers." (PMID 30739913, 2019).
ulcerative colitis (14 papers, 2020 to 2025). An inflammatory bowel disease involving the mucosal surface of the large intestine and rectum. "Hence, the current study aimed to investigate the ameliorative effect of rebamipide in a rat model of acetic acid-evoked ulcerative colitis and the linked mechanisms pertaining to SIRT1/FoxO3a/Nrf2 and PI3K/AKT pathways." (PMID 37111290, 2023). "Ample evidence has revealed that SIRT1 depletion is engaged in the pathogenies of inflammatory diseases including ulcerative colitis." (PMID 37111290, 2023). "Loganin inhibited macrophage M1 polarization and regulated SIRT1/NF-κB signaling pathway to reduce ulcerative colitis." (PMID 37483618, 2023). "Ginsenoside Rk2 prevented ulcerative colitis by inactivating the ERK/MEK pathway via SIRT1." (PMID 37483618, 2023). "UMB ameliorated acetic acid-induced ulcerative colitis by modulating TLR4/NF-κB-p65/iNOS and SIRT1/PPARγ signaling pathways." (PMID 37483618, 2023). "In a clinical trial of SIRT1 activators in mild to moderate ulcerative colitis, SRT2104, a SIRT1 activator, was well tolerated." (PMID 32823491, 2020). "Regarding the relationship between CANA and SIRT1, it has been reported that SIRT1 is upregulated by CANA, resulting in decreased oxidative stress and improved energy metabolism, thereby leading to cardiovascular protection and the amelioration of ulcerative colitis." (PMID 39940750, 2025).
age-related macular degeneration (13 papers, 2012 to 2025). Age-related loss of vision in the central portion of the retina (macula), secondary to retinal degeneration. "In this study, we investigated the role of hypoxia induced SIRT1 in choroidal neovascularization in relation to age-related macular degeneration." (PMID 22275802, 2012). "The SIRT1 activation by RSV has been demonstrated to alleviate the photoreceptor damage in retinal diseases, such as the age-related macular degeneration (AMD) and the diabetic retinopathy (DR)." (PMID 37388281, 2023). "A correlation between Sirt1 expression and LINE-1 promoter methylation levels has been identified in the human retina in the context of age-related macular degeneration (AMD)." (PMID 35058771, 2021). "The treatment of RPE cells with resveratrol, which increases SIRT1 activity, suppresses inflammatory cytokine-induced vascular endothelial growth factor (VEGF) secretion, which is involved in age-related macular degeneration (AMD)." (PMID 26583059, 2015).
Atrophy (13 papers, 2018 to 2026). Any weakening or degeneration, especially through lack of use. "Brain structural magnetic resonance imaging (MRI) showed that adeno-associated virus (AAV) mediated hippocampal Sirt1 knockdown caused hippocampal atrophy in 8-month-old mice." (PMID 35668361, 2022). "Animal studies reveal reductions in hippocampal sirtuin-1 with chronic stress and show that pharmacologic or genetic inhibition of sirtuin-1 increases stress-dependent behavioural changes and dendritic atrophy, while activation blocks these outcomes." (PMID 37153459, 2023). "Collectively, these results suggest that the polyphenolic compounds most likely exerted their beneficial effects on muscle phenotype and function through the action of sirtuin-1, as also previously reported in models of disuse muscle atrophy." (PMID 34443492, 2021). "On the other hand, another study demonstrated reduced SIRT1 activity in the hippocampus of chronic ultra-mild stress-treated mice, and increased SIRT1 activation reversed the stress-induced dendritic atrophy and anhedonia in mice." (PMID 30271963, 2018). "In a mouse model, hippocampal SIRT1 gene knockout led to hippocampal atrophy in 8-month-old mice." (PMID 37718350, 2024). "Therefore, activation of SIRT‐1 might be critical for FGF19 to attenuate PA‐induced muscle atrophy, metabolic disturbance and the decline in FNDC‐5/irisin expression." (PMID 33751819, 2021). "In this study, modulation of the sirtuin 1/angiotensin II type 1 receptor (Sirt1/AT1R) pathway partially attenuated renal glomerular sclerosis, tubular atrophy, and interstitial fibrosis in D-galactose (D-gal)-induced accelerated aging mice." (PMID 38415902, 2024). "In muscle atrophy model mice, intramuscular injection of GqDNVs improves the cross-sectional area of the quadriceps muscle, grip strength and the AMPK/SIRT1/PGC1α pathway expression." (PMID 38778385, 2024). "Another important regulator of muscle metabolism is AMPK, SIRT1 and PGC-1α signaling, displaying a crucial role in the prevention of age-related muscle atrophy by deacetylation of NF-kB and downregulation of FOXO1, respectively." (PMID 39728000, 2024).
diabetic neuropathy (13 papers, 2020 to 2025). A chronic, pathological complication associated with diabetes mellitus, where nerve damages are incurred due to diabetic microvascular injury involving small blood vessels that supply these nerves, resulting in peripheral and/or autonomic nerve dysfunction. "A study found that hesperidin can protect the oxidative stress response caused by diabetic neuropathy from oxidative damage by upregulating SIRT1 and inhibiting the expression of NOX4, one of the key sources of reactive oxygen species (ROS) production." (PMID 38983771, 2024). "Indeed, SIRT1 activation is a major target of interest for diabetic neuropathy, which is associated with high levels of serum protein glycation." (PMID 38302501, 2024). "Among the NAD+ consuming enzymes, sirtuin–1 (SIRT1) is unique because the activation of SIRT1 protects against diabetic polyneuropathy (DPN)." (PMID 38256175, 2024). "Deacetylation of FOXO3a by SIRT1 decreased oxidative stress in the N2A cells and helped to alleviate mitochondrial dysfunction, which helped to manage diabetic neuropathy, according to another study performed on STZ-induced diabetic mice." (PMID 39062016, 2024). "In the studies of diabetic neuropathy, polydatin also facilitates mitochondrial biogenesis and oxidative metabolism possibly by stimulating sirtuin 1 (SIRT1) and nuclear factor erythroid 2-related factor 2 (NRF2) axis." (PMID 35453351, 2022). "Several preclinical studies revealed that SIRT1 overexpression/activation can prevent diabetic neuropathy in experimental animals." (PMID 34071497, 2021). "SIRT1 can regulate neuronal cell fate in diabetic neuropathy by regulating metabotropic glutamate receptor (mGluR)." (PMID 34071497, 2021). "Resveratrol can prevent neurotoxicity by improving redox status and impairing inflammation in diabetic neuropathy by endorsing SIRT1 activation." (PMID 34071497, 2021). "Furthermore, it enhances mitochondrial function and Sirt1 expression in diabetic neuropathy, promoting nerve regeneration and alleviating pain." (PMID 40958722, 2025). "High levels of NAD+ can activate sirtuins, specifically SIRT1, and prevent a decrease in the IENFD in experimental diabetic neuropathy." (PMID 38256175, 2024). "SIRT1 activation by SRT1720 has been found to relieve pain behavior and trigger spinal neuronal activation in rats having painful diabetic neuropathy." (PMID 34071497, 2021). "SIRT1 activation by isoliquiritigenin can alleviate oxidative stress and mitochondrial impairment in vitro and in vivo by endorsing PGC1α/FOXO3a/AMPK signalling in experimentally induced diabetic neuropathy." (PMID 34071497, 2021).
diffuse large B-cell lymphoma (13 papers, 2012 to 2026). "The aim of the study was to explore the association between the SIRT1 single nucleotide polymorphism (SNP) rs3758391 and diffuse large B cell lymphoma (DLBCL) in a Chinese Han population." (PMID 30377410, 2018). "Kan and colleagues demonstrated that the SIRT1 rs3758391 polymorphism is associated with both the risk and survival outcomes of diffuse large B-cell lymphoma (DLBCL) in the Chinese Han population." (PMID 40507674, 2025). "Furthermore, NCAPD3 accelerates the progression of diffuse large B-cell lymphoma by recognizing H3K9 monomethylation (H3K9me1) on the SIRT1 promoter, which is connected to the SIRT1 promoter by TFII I, and increasing SIRT1 transcription." (PMID 39479446, 2024). "Sirt1 is closely related to cells aging, and Sirt1 also plays an important role in diffuse large B-cell lymphoma (DLBCL)." (PMID 32570218, 2020). "Immunohistochemical expression of SIRT1 was evaluated in patients with diffuse large B-cell lymphoma (DLBCL), using a 2 mm tissue microarray core, and SIRT1 was expressed in 74% (77/104) of patients." (PMID 27793039, 2016).
Hepatitis (13 papers, 2017 to 2025). Inflammation of the liver. "We confirmed the pattern of enhanced Ikaros/increased pyroptosis (GSDMD) being negatively associated with SIRT1 in liver-infiltrating CD11b+ cells in a murine LPS/D-Galactosamine hepatitis model." (PMID 34871625, 2022). "PARP inhibitors also attenuate PARP activation and retard the development of liver damage in hepatitis models, and these benefits are related to Sirt1." (PMID 34684653, 2021). "Although studies have reported the involvement of signaling pathways such as the sirtuin 1 (Sirt1)-signaling pathway in the progression of hepatitis steatosis, the detail molecular mechanisms are yet to be deciphered." (PMID 33771967, 2021). "The findings suggest that resveratrol protected against Con A-induced hepatitis in aged mice by attenuating an aberration of immune response and liver regeneration, partially via the mechanism of SIRT1-mediated repression of p66shc expression." (PMID 28578410, 2017). "Resveratrol pretreatment conferred protection against Con A-induced aggravation of hepatitis in aged mice by attenuating aberrations of immune response and liver regeneration, at least in part, through SIRT1-mediated repression of p66shc expression." (PMID 28578410, 2017). "This study investigated the effect of resveratrol on concanavalin A (Con A)-induced hepatitis in aged mice and the roles of SIRT1 and p66shc." (PMID 28578410, 2017). "Furthermore, SIRT1 disruption or XBP1s overexpression in macrophages exacerbated APAP-triggered liver inflammation and augmented NLRP3/caspase-1 activity in MSC-administrated mice." (PMID 35842731, 2022). "Similarly, our results showed that nobiletin increased SIRT-1 expression and upregulated PGC-1α to promote mitochondrial biogenesis and dynamics, thus attenuating hepatic IR injury." (PMID 31028246, 2019).